AQP9 (aquaporin 9)
Diseases named in the same sentence as AQP9 in open-access papers (continued):
Sharing a sentence is not in itself a finding about the gene and the disease.
cancer (continued). "Our study demonstrated that elevated AQP9 expression was significantly correlated with cancer progression, poor survival and immune infiltrations in ccRCC patients from multiple cohorts." (PMID 31703694, 2019). "Future research is required to explore the detailed mechanism between distinct AQP9 and carcinogenesis of ccRCC and reveal the mechanism of AQP9 in other carcinomas." (PMID 31703694, 2019). "The results showed that AQP9 is significantly induced in cancer tissues than that in adjacent cancer tissues." (PMID 27187384, 2016). "In our study, overexpression of AQP9 made the cancer cells sensitive to apoptosis both in vitro and in vivo conditions." (PMID 27329843, 2016). "In addition, IGF downregulates AQP9, whereby restrains intracellular H202 levels and promotes cancer stem-like properties." (PMID 37922108, 2024). "In HCC cells, lung carcinoma cells and leukemia cells, AQP9 was shown to be a transporter important for arsenic uptake, and its expression influenced the sensitivity of cells to arsenic treatment, thereby reducing the arsenic resistance of cancer cells." (PMID 38136293, 2023). "The homogenous expression of AQP3, AQP7 and AQP9 suggests that the cancer cells have a high capacity for glycerol uptake, which may contribute to the increased energy consumption of the cancer cells." (PMID 37681917, 2023). "Interestingly, AQP9 has also been reported as a prognostic indicator of many cancers in recent years and is related to immune infiltration." (PMID 36792688, 2023). "In view of the correlation between long-term chronic IBD and AQP9, determining whether AQP9 plays a role in the transformation of IBD into cancer is a very valuable research direction." (PMID 36792688, 2023). "Then, we compared the expression levels of AQP9 with cancer prognosis." (PMID 35972604, 2022). "AQP9 (aquaporin 9) has been extensively reported in cancer but with contrasting observations." (PMID 34830779, 2021). "Recently AQP9 has also been found to play opposite roles in progression of different cancers." (PMID 34475994, 2021). "Taken together, our findings suggested that AQP9 had significant prognostic value in several distinct types of cancers and different AQP9 expression levels had different prognostic impact that might depend on the specific type of cancers." (PMID 33247170, 2020). "In view of the correlation of AQP9 expression with immune infiltrating levels in diverse cancers, we then examined the specific cancer types in which AQP9 can play a role as a prognostic biomarker and is significantly associated with immune infiltration levels." (PMID 33247170, 2020). "In our analysis, we explored 39 types of cancer in TIMER to determine whether AQP9 expression was related to the abundance of immune infiltration in diverse cancers." (PMID 33247170, 2020). "Additionally, we also found significant correlations of AQP9 with 28 types of TILs across human heterogeneous cancers." (PMID 31703694, 2019). "Thus, ATO uptake via AQP9 regulates its ability to induce Pin1 degradation and inhibit cancer cells." (PMID 30093655, 2018). "The fact that AQP9 providesAPL cancer cell specificity with high response rates suggests that if arsenic-containingcompounds could be targeted for specific delivery into cancer cells, then theywould represent outstanding agents for killing these cells." (PMID 18431449, 2008). "Thus, the homogenous expression of AQP3, AQP7 and AQP9 may aid the cancer cells in their adaptations to high osmotic stress as well as facilitate H2O2-mediated signaling—both of which may aid cancer cell survival." (PMID 37681917, 2023). "Moreover, it was been shown that gene markers of M2 macrophages were moderately to very strongly correlated with AQP9 expression, suggesting that AQP9 might be involved in the polarization of TAMs and in the immunosuppression in cancer." (PMID 34012923, 2021).
cancer (continued). "Further researches are needed to determine whether AQP9 can be used to transport substances that are beneficial to the treatment of tumors so as to improve the clinical prognosis of patients with different cancers." (PMID 33247170, 2020). "Up-regulation of AQP9 expression may enhance the cytotoxic effect of ATO against cancer cells." (PMID 32010690, 2019). "However, when cancer cells developed to androgen-independent, the role of AQP9 in cancer cells remains unclear." (PMID 27187384, 2016). "AQP9 is downregulated by insulin-like growth factor 2 (IGF2), which is crucial for cancer stem cell stemness maintenance." (PMID 39125952, 2024). "Therefore, AQP9 may be an important target related to a variety of cancers." (PMID 33247170, 2020). "Western blotting was also used to determine the expression of AQP9 protein in HCC and matched para-carcinoma tissues." (PMID 31969493, 2020). "MMP (matrix metalloprotein) family play an important role in invasion and metastasis of cancer cells; therefore, the expression of MMP9 between control and AQP9-siRNA were conducted." (PMID 27187384, 2016). "Therefore, the downregulation of AQP9 may present as a target for cancer therapy." (PMID 24959239, 2014). "AQP9 overexpression results in intracellular H2O2 accumulation, attenuation of β-catenin/TCF4 interaction, dissociation of β-catenin from FOXO3a (ultimately resulting in β-catenin activity inhibition), and cancer stem cell stemness suppression." (PMID 39125952, 2024). "Overall, several AQPs, including AQP1, AQP3, AQP4, AQP5, AQP8, and AQP9, have been suggested to transport H2O2, and their expression promotes cancer cell growth and migration, However, solid data exist only for AQP3- mediated H2O2 transport as one of the key mechanisms for cancer cell migration." (PMID 35847914, 2022). "However, when TNBC cells are treated with ATO and ATRA, ATRA induces AQP9 and increases the uptake of ATO by cancer cells, while at the same time ATRA cooperatively inhibits Pin1 as well as other oncogenic pathways, such as NF-κB, β-catenin, c-Myc, Akt, and c-Jun." (PMID 38136293, 2023). "Furthermore, GO analysis demonstrated that genes co-expressed with AQP9 were significantly enriched in immune related gene sets in BRCA, COAD, LUAD, LUSC and STAD, which could be used as chemotherapeutic targets for cancer treatment." (PMID 33247170, 2020). "How AQP9 overexpression sensitizes cancer cells to apoptosis is not quite clear." (PMID 27329843, 2016).
infection (12 papers, 2009 to 2025). The state of being infected such as from the introduction of a foreign agent such as serum, vaccine, antigenic substance or organism. "Given the suggested involvement of AQP3 and AQP9 in infection, inflammation, and the development of disease, we investigated the contribution of these two AQPs to leukocyte phagocytosis." (PMID 40558507, 2025). "The depletion of AQP9 in a murine model resulted in deficient neutrophil and T cell activation, while in macrophages AQP9 is a key player for the sensing system towards infection by Pseudomonas aeruginosa." (PMID 39125952, 2024). "AQP9, highly expressed in septic patients, is essential for neutrophil migration and activation, both of which are critical for controlling infection." (PMID 39544938, 2024). "Such activation induces AQP9 upregulation with consequent changes in cell shape and motility, confirming its pivotal participation in infection, inflammation, and clearance/disease progression." (PMID 39125952, 2024). "In fact, the dramatic effect of AQP9 silencing on infection by P. berghei was also somewhat unexpected, because it is well known that human HepG2 hepatoma cells can be readily infected by this parasite, despite undetectable AQP9 expression." (PMID 34268141, 2021). "Pharmacologic inhibition of AQP9 by phloretin during the first two hours of hepatocyte co-incubation with sporozoites resulted in a significant reduction in hepatocyte infection in a dose-dependent manner." (PMID 34268141, 2021). "To investigate the potential role of AQP9 in human hepatocyte infection by P. falciparum sporozoites, we performed AQP9 gene silencing using five smalls interfering RNAs (siRNAs)." (PMID 34268141, 2021). "We have recently shown that infections with P. aeruginosa do increase the AQP9 expression in macrophages, and that bacteria with a fully functional QS-system provoke a larger increase compared to a mutant lacking 3O-C12-HSL and C4-HSL." (PMID 27047801, 2016). "A similar delay in P. berghei blood stage infection of Swiss-Webster mice, as seen for the aqp− parasite line, was observed when WT P. berghei parasites were grown in aqp9−/− mice." (PMID 23137753, 2012). "Interestingly, the magnitude of the effect of AQP9 silencing in human hepatocytes on infection by P. falciparum, either on parasite entry or on the number of schizonts, is comparable to that of CD81 silencing." (PMID 34268141, 2021). "Moreover, chemical disruption with the AQP9 inhibitor phloretin markedly inhibited hepatocyte infection." (PMID 34268141, 2021). "Sensing bacterial QS molecules and responding by cell swelling facilitated via AQP9 could be a danger signal and a way for the macrophage to prepare for migration to the site of infection." (PMID 27047801, 2016). "In this report, we have discovered and added one more player to infection and inflammatory events, since we noted that P. aeruginosa specially one with a working QS system lasI/rhlI induces increased AQP9 expression, re-organization and changes in macrophage size." (PMID 26388857, 2015). "In this work, we investigated the expression and involvement of AQP3 and AQP9, two aquaglyceroporins also permeable to hydrogen peroxide, in important processes of immunity such as cell migration, and the phagocytosis and killing of ingested bacteria by WBCs following infection." (PMID 40558507, 2025). "In this study we described the initial characterization and effects of a novel small molecule AQP9 inhibitor, RG100204, in a cecal ligation and puncture (CLP) induced model of polymicrobial infection." (PMID 35774785, 2022). "But after 1-h infection with wild type P. aeruginosa and lasI-/rhlI- mutant at all MOI, we observed remarkable alterations in intensity and localization of AQP9." (PMID 26388857, 2015).
infection (continued). "After 1-h infection with wild type P. aeruginosa at MOI 10, we observed more distinct AQP9 localization in the cytoplasm at peripheral regions in vicinity of leading- and trailing- edges and in protruding structures, i.e., in filopodia and lamellae." (PMID 26388857, 2015). "The involvement of AQP3 and AQP9 in bacterial killing was evaluated by measuring the percentage of bacterial survival at 10, 30, and 120 min of infection in the presence or not of 10 μM DFP00173 or HTS13286 or both inhibitors added together." (PMID 40558507, 2025). "Among the most downregulated genes in the non-permissive cells, we focused on that coding for aquaporin-9 (AQP9), a water and glycerol channel previously shown to be involved in mice susceptibility to P. berghei blood stage infection." (PMID 34268141, 2021). "P. berghei schizont diameters measured two days post-infection were similar in AQP9-knockout and wild type hepatocytes thus confirming that AQP9 is not involved in parasite development at the liver stage." (PMID 34268141, 2021). "Overall, as a membrane-bound protein highly expressed in infection-permissive cells and almost silent in non-permissive cells, hepatocyte AQP9 is a candidate protein that could be involved in sporozoite entry into cells." (PMID 34268141, 2021). "Transgenic mice lacking the aquaglyceroporin AQP9 (defective in the rapid uptake of glycerol) can support growth of P. berghei, but the lethal effects of infection are delayed, suggesting that uptake of glycerol plays a role in virulence in P. berghei infection." (PMID 19040641, 2009).
bacterial infection (4 papers, 2015 to 2025). "Accordingly, we decided to investigate the role of AQP9 during bacterial infection." (PMID 26388857, 2015). "No apparent involvement of individually blocked AQP3 or AQP9 was observed in the phagocytosis of K. pneumoniae by neutrophils or monocytes after 10, 30, or 60 min of bacterial infection." (PMID 40558507, 2025).
benign tumor (2 papers, 2014 to 2018). "The expression of AQP1, AQP5 and AQP9 are significantly higher in malignant and borderline ovarian tumors than benign tumors and normal ovarian tissues." (PMID 24918928, 2014).
brain disorder (2 papers, 2016 to 2023). A disease affecting the brain or part of the brain. "However, as far as we know, no reports have linked AQP9 to brain disorders in humans." (PMID 27218255, 2016).
metabolic disorders (2 papers, 2018 to 2022). "AQP7 and AQP9 represent glycerol channel in adipose tissue and liver and have been associated with metabolic diseases." (PMID 30598999, 2018). "However, thus far, there is a lack in association studies of AQP9 gene and metabolic disorders." (PMID 30598999, 2018). "There is evidence of a lower hepatic AQP9 expression and glycerol permeability in females compared to males potentially contributing to a less severity of females in metabolic disorders." (PMID 36293210, 2022). "However, no study so far, investigates the association of human AQP9 gene and metabolic disorders." (PMID 30598999, 2018).
AQP9 also shares sentences with these, for which no sentence is quoted: myocardial infarction (4 papers); Multiple Organ Failure (3); Alzheimer disease (2); Hypertension (2); ischemic stroke (2); lactic acidosis (2); malnutrition (2); sudden infant death syndrome (2); type 1 diabetes (2); alcoholic steatohepatitis (1); breast tumors (1); cervical cancer (1); Cirrhosis (1); colon adenocarcinoma (1); congestive heart failure (1); ductal carcinoma (1); endocarditis (1); endometrioid ovarian cancer (1); Epididymis (1); epithelial ovarian tumors (1); esophageal cancer (1); gestational diabetes (1); graft versus host disease (1); head and neck cancer (1); hematoma (1); hypoxic-ischemic encephalopathy (1); immune disorders (1); irritable bowel syndrome (1); kidney cancer (1); leishmaniasis (1).
A further 16 diseases each share a sentence with AQP9 in 1 paper.